CD4 (CD4 molecule)
Diseases named in the same sentence as CD4 in open-access papers (continued):
Sharing a sentence is not in itself a finding about the gene and the disease.
tumor (continued). "This evidence for direct CD4+ T cell cytotoxicity against patient tumors does not preclude other CD4-dependent effector functions in anti-tumor immunity." (PMID 34910940, 2021). "Taken together, the in silico analysis indicates that the density of tumor infiltrating immune cells like B cells, CD8+ T cells, CD4+ T cells, macrophages, neutrophils and dendritic cells is mostly paralled by the expression of selective markers of immunmodulation." (PMID 33805268, 2021). "There was no significant decrease in the CD4:CD8 ratio in tumour tissue, although there is a suggestion of such a decrease in epithelium (intratumoural tissue)." (PMID 33257839, 2021). "Tumor-infiltrating CD11b+ B cells displayed higher levels of MHC-II compared to their CD11b− counterparts in the αCD40-treated groups, indicating an increased capability to interact with CD4+ T cells." (PMID 34226552, 2021). "Interestingly, the number of TILs recovered from UM and CM were similar, but after two weeks of culture in the presence of IL-2, UM-derived TIL cultures were mainly CD4+T cells and produced IFN-γ in response to parental tumor cells." (PMID 33922591, 2021). "In contrast, the percentage of CD4+ T cells within the tumor treated with the combination was not significantly different from those for the other three groups." (PMID 34771497, 2021). "Another difference we detected was that tumor PD-L1 expression correlated with TILs (CD4, CD8) and macrophages (CD68) in extracerebral sites but not in the brain." (PMID 32974852, 2021). "On the other hand, both CD4+ and CD8+ lymphocytes, as well as NK cells, are known to induce PD-L1 expression on tumor cells through an IFN-γ mediated mechanism; therefore, it might be possible that an immune-rich TME could in turn induce PD-L1 expression." (PMID 34122444, 2021). "CD8 and CD4 T cell produce IFN-γ during the adaptive immune response which favors Th1 cell expansion, and expression of IFN-γ has been shown to upregulate MHC class I on tumor cells and increase cytotoxicity of natural killer cells and cytotoxic T cells." (PMID 34504657, 2021). "Profiling of tumor-draining LNs of mice showed that migratory cDC2s expressing CCR7 were responsible for initiating CD4+ T cell priming, but not differentiation, leading to defective anti-tumoral effector T cells." (PMID 34566965, 2021). "Th2 cells, characterized as CD45+CD4+CCR4+, were decreased at the tumour site upon ITPP treatment." (PMID 33624446, 2021). "T cell distributions within the peribronchial regions (areas surrounding the tumors rather than within the tumor itself) were also examined revealing accumulations of CD4+ T cells in the double cKO and Gsk3a cKO but not the Gsk3b cKO mice." (PMID 34142056, 2021). "For example, the naïve T cells were significantly enriched in the nonmalignant tissue (P < 0.001), while the CD4+ T helper cells and cycling T cells were enriched in the tumor tissue (P = 0.0011 and 0.018, respectively)." (PMID 33463049, 2021). "Treg are defined as a T helper cell subpopulation characterized by the co-expression of CD4, CD25, and in large parts of FoxP3, which inhibit the activation and differentiation of CD4+ and CD8+ T cells, subsequently impairing reactivity against autologous and tumor-expressed antigens." (PMID 33430105, 2021). "Furthermore, we observed a significant decrease in the frequency of PD1+ CD4+ cells in the spleen, as well as a decrease in PDL1 expression in tumor cells, suggesting strongly that the vaccination protocol had overcome the T-lymphocyte anergy." (PMID 34957134, 2021). "In fact, in pre-clinical and clinical studies, adenoviruses armed with cytokines such as GMCSF, TNFa and IL-2 conferred improved anti-tumor response, with enhanced effector CD8+ T and helper CD4+ T cell trafficking into tumors, when compared to their unarmed versions." (PMID 34084172, 2021).
tumor (continued). "We emphasize the need to better understand the dynamics of tumor antigen-specific CD4 T cell responses, as opposed to bulk studies, to dissect the contribution of tumor-specific versus bystander T cell responses." (PMID 34064410, 2021). "Overall, the balance of the different T cell subsets in favor of lower levels of CD8+ T cells compared to CD4+ T cells, and TIM-3+ NK cells, which can further dampen T cell responses within CRC TME, highlighting an immune tolerant environment to aid tumor progression." (PMID 33477864, 2021). "Whole tumor cells usually express all TAAs and tumor-specific antigens (TSA), both known and unknown, leading to simultaneous induction of CD8+ and CD4+ cells." (PMID 35083010, 2021). "Interestingly, the contribution of CD107a to identifying the repertoire of tumor-specific reactive TILs was negligible in both the CD8+ and CD4+ TIL compartments." (PMID 34707600, 2021). "Additionally, there was a reduction in CD163+CSF1R+ macrophages in tumor tissue and increased CD8:CD4 ratio in response to treatment." (PMID 34868044, 2021). "Upon examining T-cell subpopulations, we observed that there was an increase in the percentage of CD4+ T cells in the nonirradiated, right hindlimb tumor of mice that received PDT, relative to all treatment controls." (PMID 36405502, 2021). "CD4+ regulatory T cells, myeloid derived suppressor cells and macrophages (MØs) infiltrate early during PDA development, and directly promote tumour progression through matrix metalloproteinase (MMP) and IL6 signalling, while simultaneously suppressing anti-tumour immunity." (PMID 34921158, 2021). "We found that patients with high-risk score was negatively correlated with infiltrating neutrophils, macrophages, dendritic cells, B lymphocytes, CD4+ T lymphocytes and CD8+ T lymphocytes in the tumor microenvironment (p<0.05), indicating a universal decrease of infiltrating immune cells." (PMID 34150632, 2021). "A six-plex panel was specifically designed to interrogate the tumour-immune microenvironment and included a tumour-related protein (cytokeratin), a functional marker for proliferation (Ki67) and four immune-related T-cell lineage markers (CD3, CD4, CD8 and Foxp3)." (PMID 33742063, 2021). "Dendritic cells linking the innate and adaptive immune responses activate CD4+ and CD8 + T cells by presenting the specific-antigens, to play the indirect role in anti-tumor immunity; however, the process may be lost or attenuated in TME." (PMID 34116604, 2021). "The data indicate that a chemotherapy-induced up-regulation of CD8+ TNFR2+ and CD8+ TNFR2+ PD-1+ TILs at the expense of CD4+ TNFR2+ FOXP3+ TILs and CD4+ TNFR2+ PD-1+ TILs was connected to reduced tumor growth, possibly through alteration in anti-tumor immune activities." (PMID 34201054, 2021). "Additionally, analysis of cytotoxic T cells indicated that the IFN-γ+ CD4+ T cells and IFN-γ+ CD8+ T cells increased 3.8- and 5.7-fold, respectively, in H22 tumor-bearing mice after treatment with AAGL." (PMID 33710817, 2021). "In the present study, we aimed to characterize the population of tumor-infiltrating immune cells (CD3+, CD4+, CD8+, Foxp3+, and CD57+) along the ACS, and to uncover potential differences between adenomatous and invasive lesions in the sporadic setting versus the hereditary (FAP-related) context." (PMID 34575971, 2021). "Our results imply that exhausted CD4 TILs could also contribute to B cell recruitment and TLS formation within the tumor microenvironment." (PMID 33332284, 2021). "Th17 cells and CD4+ CD25+ Foxp3+ regulatory T cells, and immunoregulatory cytokines such as TGF-β, may play equivocal roles in tumor development, depending on their context within the TME and triggering events leading to initial propagation of carcinogenesis." (PMID 34930302, 2021).
tumor (continued). "We quantified that shift by comparing the proportion of each cell population based on their responder status and found that responders had increased levels of infiltrating CD4 T cells, CD8 T cells, and NK cells, while the proportion of tumor cells was considerably lower." (PMID 34433873, 2021). "The number of CD83+ DCs was considered a marker of good prognosis, and their density positively correlated with the number of CD4+ or CD8+ T cells, thus, suggesting that higher frequencies of mature tumor-infiltrating DCs favor the activation of tumor-specific immunity." (PMID 34062821, 2021). "In these tumor conditions, GD3 has been reported to contribute not only to the promotion of tumor cells, but to the suppression of antitumor immunity by inhibiting the functional activities of dendritic cells and CD4 T cells." (PMID 33859643, 2021). "Meanwhile, SPP1 was also a potential ICI inhibitor and could not only up-regulate PD-L1 on the surface of TAMs but also decrease the anti-tumor effect of CD8+T and the activation of CD4+T cells." (PMID 34804043, 2021). "Besides, in OC, sHLA-G1/G5 is negatively correlated with CD3-/CD56+ subgroups and CD4+ CD45RO+ memory cells, suggesting that sHLA-G plays a role in the tumor microenvironment by up-regulating T-reg cells and down-regulating NK cells." (PMID 34868081, 2021). "Importantly, using genetically engineered mice, selective deletion of Nhe1 from Cx3cr1+ microglia/myeloid cells elevated CD4+PD-1+ and CD8+PD-1+ tumor infiltration in response to TMZ monotherapy." (PMID 33391535, 2021). "Others found that neoadjuvant ablation of Tregs in 4T1 tumor–bearing Foxp3DTR mice almost completely abolished the formation of lung metastases, which was dependent on both CD4+ and CD8+ T cells but not NK cells." (PMID 34632244, 2021). "Notably, we observed that MTR-OralGem administration markedly increased the percentages of tumor-infiltrating CD3+CD8+PD-1+ and CD3+CD4+PD-1+ T cells, compared to MTD-Gem treatment." (PMID 33920884, 2021). "IL-35 can influence the transcription and expression of T cell immune response-related differentially expressed genes in tumor tissues, but the immunosuppressive activity of this cytokine is primarily attributable to its inhibition of CD4+ and CD8+T cells and of anti-tumor immune responses." (PMID 34093586, 2021). "A prominent increase in the CD4+ effector T‐cell fraction was induced in tumor‐bearing lungs without concomitant changes in Tregs." (PMID 33152115, 2021). "Additionally, CD4 Th1 cells also display antitumor responses by activating NK cells and M1 TAM, inhibition of angiogenesis, and/or induction of tumor senescence." (PMID 35003090, 2021). "TAMs represented the major component of the immune infiltrate, while TILs accounted for only a small minority (~0.5%) of tumor cell population, and their lack was aggravated by the total absence of CD4 T cells." (PMID 33674596, 2021). "CD4 and CD8 cells were present either in the tumor stroma or between cancer cells." (PMID 34778030, 2021). "Tumor-derived ExVs were able to increase the activation of caspase-3, caspase-7 and caspase-9 and down-regulate the anti-apoptotic proteins, including BCL-2, MCL-1 and BCL-xL, in CD4+T cells." (PMID 33435564, 2021). "In mice injected subcutaneously with a tumor cell line, tumoral accumulation of Tregs but not conventional CD4+ CD25-Foxp3- T cells was significantly reduced by CCR2 deficiency." (PMID 34804061, 2021). "Additionally, CD4+ T cells secrete inhibitors of angiogenesis (e.g., CXCL9 and CXCL10) which can indirectly contribute to tumor dormancy by stabilizing the endothelium." (PMID 33738282, 2021). "While most studies of tumor and blood suggest that changes in CD8+ T cells correlate with ICB outcomes, other T cell populations in the MPE, such as CD4+ helper T cells, could also be predictive of ICB outcomes." (PMID 33987104, 2021). "The IHC imaging showed that the irradiated tumor had increased CD8+ and CD4+ cells." (PMID 33669885, 2021).
tumor (continued). "Flow cytometry confirmed that after 177Lu-DOTA-Y003 injection, CD8+ T cell upregulation occurred in the tumor microenvironment, but there was no obvious change in CD4+ T cells." (PMID 33391476, 2021). "Moreover, the proportion of CD4+ T cells and CD8+ T cells in the CTX + J was higher than that in the CTX group, suggesting enhanced tumor-killing effects." (PMID 34444860, 2021). "Similarly, the densities of CD3+, CD4+, CD8+, CD45RO+, and CD56+ tumor-infiltrating immune cells were assessed." (PMID 34572935, 2021). "Additionally, we observed an increase in total CD3+ cells, a significant decrease in CD4+ T cells and a significant increase in CD8+ T cells in the tumour-rechallenged site of ICRP-KCC mice, when compared with naive mice." (PMID 33531687, 2021). "This may be related to the Th1 cells among CD4+ T cells that activate CD8+ CTLs and promote the immune system to suppress tumor progression." (PMID 34367978, 2021). "Unlike CD8+ T cells, CD4+ T cells were observed to be located only in the cancer margin with no invasion into the tumor epithelium in p16INK4A negative CRC." (PMID 33643790, 2021). "There is a significant decrease of CD8+/CD4+T cells ratio, NK cells, IL-2, and IFN-γ and a significant increase of T regs, IL-6, IL-1β, TNF-α, IL-10, and PGE2 in CUMS group, indicating the inhibition of immunity in the tumor microenvironment." (PMID 34422050, 2021). "A lack of in vivo activation and the weak tumor-specificity of adoptively transferred CD4+T cells remain a major challenge in the long term success of ATCT." (PMID 33918403, 2021). "Furthermore, flow cytometry analysis revealed that tumor‐infiltrating CD3+ cells were greatly increased in the treated tumors and were accompanied by an elevation of CD8+/CD4+ ratios." (PMID 34766145, 2021). "Our current working hypothesis is that peripheral administration of CXCL10-Ig or CXCL9-Ig would induce the activity of CXCR3+ effector CD4+ T cells, effector CD8+ T cells, and NK cells that are then recruited to at the tumor sites to limit cancer." (PMID 34944943, 2021). "To validate whether ITH was also reflected by tissue immune cell density, we next examined the heterogeneity in the densities of the CD4+ and CD8+ T cells within tumour tissues using multiplex immunohistochemistry (mIHC) (left)." (PMID 33431814, 2021). "In addition, a microsatellite‐stable colon cancer patient receiving IT1208 treatment showed increased infiltration of both CD4+ and CD8+ T cells in the tumor and achieved a durable partial response." (PMID 34977870, 2021). "Depletion of CD4+ and CD8+ T cells completely reversed the anti-tumor effect of VTX+ CTX." (PMID 33452311, 2021). "Whether CD4+ T cells, and which subsets thereof, are targeted in cancer patients treated with CPI can be addressed in biomarker studies either within the tumor itself, or in the blood as discussed in the previous section." (PMID 33546283, 2021). "The mRNA vaccines delivered in lipid nanoparticles intravenously can also elicit strong CD4 and CD8 specific T cell responses against non-mutated tumor associated antigens (TAAs) alone or in combination with anti-PD-1 blockade." (PMID 34064410, 2021). "CD4+ T cells have an important regulatory effect, and CD8+ T cell stem cell-like subgroups have the potential to self-proliferate and differentiate toward effector cells, which can produce durable anti-tumor immune response and specifically kill tumor cells." (PMID 34490243, 2021). "We observed that the proliferation of CD4+ T cells but not CD8+ T cells were significantly increased in response to SN from tumor cells exposed to GIHT alone or in combination with gamma irradiation." (PMID 34485114, 2021). "The Vectra mIHC images (left) and corresponding spatial maps (right) provide visual validation at the single-cell level that PD-1+ CD4+ T cells were closer to tumor cells in responders but closer to Tregs in nonresponders." (PMID 34795254, 2021).
tumor (continued). "For example, OX40 is upregulated on activated CD4+ and CD8+ T cells, and an agonistic antibody of OX40 synergises with an inhibitor of transforming growth factor (TGF)-β to reduce the primary tumour growth of 4T1 mammary cells as well as spontaneous lung metastasis." (PMID 33262520, 2021). "We saw a non-significant trend toward increased numbers of tumor-infiltrating CD4+ and CD8+ T cells in PeptiBAC-Trp2-treated tumors compared with BCG, anti-PD-1 alone and BCG in combination with anti-PD-1 ICI-treated tumors." (PMID 34266884, 2021). "Small molecule tracers binding to immune cell markers such as CD8, CD4, CD11b, or secreted proteins such as IFN-γ, IL-2, or TNF-α could be highly useful for characterizing the tumor immune landscape with a reduced wait time post-injection." (PMID 33391977, 2021). "Finally, we analyzed the percentage of CD3+, CD4+, and/or CD8+ T cells in the peripheral blood and dissociated tumor tissues of the treatment mice." (PMID 34054817, 2021). "Importantly, the number of CD8+ cells and CD4+ cells surrounding the PDAC tumor in the mC4BPA group were significantly higher than those in the control group (CD8+, P=0.044), (CD4+, P=0.033)." (PMID 34167573, 2021). "The anti-tumor efficacy of anti-CD20 therapy is reportedly related to antibody-dependent cytotoxicity (ADCC), including NK cells and macrophages and the involvement of CD8+ and CD4+ T cells." (PMID 34539411, 2021). "Intriguingly, these subtypes corresponded to naive-like CD8+ and CD4+ cells, and not to TILs displaying markers of tumor reactivity, such as PD-150." (PMID 34017005, 2021). "Notably, HGF NPs treatment induced the highest increase in tumor-infiltrating cytotoxic and helper T lymphocytes (CD3+CD8+ and CD3+CD4+) due to the combination of relieved immunosuppression of exosomal PD-L1 and enhanced ferroptosis." (PMID 34593794, 2021). "Therefore, we analyzed the mRNA expression of several immune cell markers (Cd4, Cd8, Klrb1c, CD27, and Adgre1) within the E0771 tumor tissues from WT and Bgn KO mice." (PMID 33966638, 2021). "Also, CD4+ TCR diversity significantly increased during treatment, as cHL is a tumor with frequent major histocompatibility complex (MHC) class I loss." (PMID 33681388, 2021). "In the A20 model, CpG significantly increased the OX40 MFI on tumor infiltrating non-Treg CD4+ and CD8+ T cells, as reported." (PMID 34868010, 2021). "CD4+TRM cells are known to be essential for cytotoxic programming of CD8+T cells, and they can also suppress tumor growth through secretion of IFN-γ or direct killing tumor cells in human NSCLC." (PMID 34707601, 2021). "Further, it has been reported that agonistic activation of 4-1BB induced CD4+ and CD8+ T cell activation, and prevented their activation-induced death, making these agonist antibodies an ideal therapeutic candidate to enhance anti-tumor immunity." (PMID 33520112, 2021). "Distinctively, both CD4+ and CD8+ T lymphocytes can be detected in close proximity to tumor cells, as well as the loco-regional liberation of pro-inflammatory cytokines that promote the activation and migration of tumor antigen specific T cells." (PMID 34869014, 2021). "Our results demonstrated that there is a robustly positive relationship between IGFBP7 expression level and infiltration of macrophages, DCs, CD4+ T cells and CD8+ T cells, which indicated that IGFBP7 may be involved in regulating tumor immunology in GC." (PMID 33531979, 2021). "In contrast to glutamine, the increased intercellular concentration of L-Arginine directly enhances remarkable metabolic reprogramming and survival capacity of CD4+ and CD8+ T cells, independently of mTOR signaling or downstream metabolites, thus, improves anti-tumor activity." (PMID 35250965, 2021).